ENSG00000206647
Synonyms: LOC124906144
Gene: Small nucleolar RNA gene on chromosome 2 (10,155,072 to 10,155,206, reverse strand). Ensembl gene ENSG00000206647.
Gene Ontology:
Biological process: RNA processing
Cellular component: nucleolus
Homologues: Paralogues in human: SNORA2A (87% identical), SNORA2C (72% identical), SNORA2B (70% identical).